BCL2 (BCL2 apoptosis regulator)
Diseases named in the same sentence as BCL2 in open-access papers (continued):
Sharing a sentence is not in itself a finding about the gene and the disease.
chronic lymphocytic leukemia (continued). "The BCL2 inhibitor venetoclax promotes apoptosis in blood cancer cells and is approved for treatment of chronic lymphocytic leukemia and acute myeloid leukemia." (PMID 37956312, 2023). "The BH3-mimetic drug Venetoclax, a specific inhibitor of anti-apoptotic BCL-2, has had clinical success for the treatment of chronic lymphocytic leukaemia and acute myeloid leukaemia." (PMID 37567974, 2023). "Preventing or overcoming resistance to the Bcl‐2 inhibitor venetoclax is an emerging unmet clinical need in patients with chronic lymphocytic leukaemia (CLL)." (PMID 36550750, 2023). "Venetoclax is a potent BCL-2 selective BH3-mimetic that is clinically approved for use in chronic lymphocytic leukemia and treatment of patients with acute myeloid leukemia who are aged or unmet for intensive induction chemotherapy." (PMID 38039297, 2023). "Encouraged by the design of venetoclax and its efficacy in chronic lymphocytic leukemia, scientists have developed other BCL-2 homology (BH3) mimetics—particularly MCL-1 inhibitors (MCL-1i)—that are currently in clinical trials for various cancers." (PMID 37601693, 2023). "The products of BCL2 and its homologs, including BAX and BCL2L12, are implicated in chronic lymphocytic leukemia (CLL)." (PMID 37424436, 2023). "Venetoclax, an FDA-approved Bcl-2 inhibitor, is quickly evolving as the standard of care for acute myeloid leukaemia and chronic lymphocytic leukaemia." (PMID 37834104, 2023). "One such clinically relevant senolytic is venetoclax, which is a small-molecule inhibitor of BCL2 used in the treatment of chronic lymphocytic leukemia and other hematologic malignancies." (PMID 36980794, 2023). "The selective Bcl-2 inhibitor Venetoclax (ABT-199) was the first compound approved for treatment of chronic lymphocytic leukemia (CLL) and certain types of acute myeloid leukemia (AML)." (PMID 35887198, 2022). "BCL2 is overexpressed in several hematological malignancies such as chronic lymphocytic leukemia (CLL) and aggressive NHL, and is targeted by venetoclax." (PMID 35326711, 2022). "Another representative example is Venetoclax, a BCL-2 inhibitor approved for clinical use to treat chronic lymphocytic leukemia and certain types of small lymphocytic lymphoma." (PMID 36432086, 2022). "ABT-199 showed 100-fold increased selectivity for Bcl-2 over Bcl-xl or Bcl-w and it was found to be more effective against Chronic Lymphocytic Leukemia (CLL) with milder cases of thrombocytopenia." (PMID 36309485, 2022). "Targeting of BCL-2 with the specific inhibitor ABT-199 (Venetoclax) has significant clinical activity in malignant diseases such as chronic lymphocytic leukemia and multiple myeloma." (PMID 35443750, 2022). "Venetoclax (ABT-199, Venclexta), a first-in-class BCL-2 inhibitor, has transformed the treatment of hematologic cancers, including chronic lymphocytic leukemia, small lymphocytic lymphoma, and acute myeloid leukemia (AML)." (PMID 35456528, 2022). "High levels of Bcl-2 expression were found in the patients of follicular lymphoma (FL), chronic lymphocytic leukaemia (CLL), mantle cell lymphoma (MCL) and Waldenstrm’s macroglobulinaemia (WM)." (PMID 36477747, 2022). "Eμ-TCL-1 transgenic mice and Traf2DN/BCL2-double-tg mice have been used in a chronic lymphocytic leukemia (CLL) study." (PMID 35746487, 2022). "Patients with chronic lymphocytic leukemia (CLL) relapsing on ibrutinib are often treated with the Bcl-2 inhibitor venetoclax." (PMID 35448201, 2022). "This is particularly true in the treatment of chronic lymphatic leukemia, typified by the approval of the BCL-2 inhibitor venetoclax as a particularly effective rescue therapy for this disease." (PMID 36071980, 2022). "The AKT/ MCL-1 signaling pathway has been reported to play a prominent role in mediating antiapoptotic signals in chronic lymphocytic leukemia B cells or in resistance to BCL-2/PARP inhibitors, or BH3 mimetics." (PMID 35136016, 2022).
chronic lymphocytic leukemia (continued). "High levels of BCL-2 can be observed in patients with follicular lymphoma (FL), chronic lymphocytic leukaemia (CLL), mantle cell lymphoma (MCL) and Waldenström's macroglobulinaemia." (PMID 35598030, 2022). "Venetoclax, a Bcl2 inhibitor, is commonly used in the treatment of chronic lymphocytic leukemia as a monotherapy, and in combination with other therapies for acute myeloid leukemia." (PMID 35261195, 2022). "This is perhaps best demonstrated in high-BCL-2-expressing chronic lymphocytic leukemia (CLL) that is often highly sensitive to the BCL-2-selective BH3-mimetic, venetoclax." (PMID 35447090, 2022). "Venetoclax (ABT‐199), a small‐molecule inhibitor selectively targeting BCL‐2, has been approved by more than 50 countries for the treatment of adult chronic lymphocytic leukaemia (CLL)." (PMID 36053810, 2022). "Venetoclax, a BCL2 inhibitor has been used effectively in a range of hematological malignancies with impressive results particularly in chronic lymphatic leukemia when used in combination with ibrutinib." (PMID 34821081, 2022). "In 2015, venetoclax (VEN), the first-in-class selective BCL-2 inhibitor, was approved for the treatment of chronic lymphocytic leukemia (CLL) patients who failed previous treatment." (PMID 35091682, 2022). "B-cell receptor (BCR) signaling pathway and Bcl-2 family prosurvival proteins, specifically Bcl-2 and Mcl-1, are functional in the pathobiology of chronic lymphocytic leukemia (CLL)." (PMID 35273915, 2022). "A unique class of small molecule BCL-2 inhibitors/BH3-mimetics that specifically block anti-apoptotic BCL-2 proteins has been developed and the BCL-2 specific ABT-199/Venetoclax showed efficacy in the treatment of chronic lymphocytic leukemia." (PMID 35443750, 2022). "Venetoclax is the only selective BCL-2 inhibitor approved for treatment of patients with chronic lymphocytic leukemia and small lymphocytic leukemia." (PMID 36167829, 2022). "Inhibition of antiapoptotic proteins as a monotherapy, (specifically Bcl-2, Bcl-xL, and Mcl-1) is a successful cancer treatment strategy for acute myeloid leukemia, chronic lymphocytic leukemia, and small lymphocytic lymphoma." (PMID 36381235, 2022). "The BCL-2 selective inhibitor venetoclax (ABT-199) has shown efficacy in different hematological malignancies such as chronic lymphocytic leukemia (CLL), acute myeloid leukemia (AML) and T-cell acute lymphoblastic leukemia." (PMID 35031695, 2022). "In line with this, E7107 was shown to sensitize chronic lymphocytic leukemia (CLL) cells to Bcl-2 inhibitor venetoclax." (PMID 34065983, 2021). "Venetoclax was the first BCL-2-selective BH3-mimetic to achieve FDA approval for Chronic Lymphocytic Leukaemia (CLL), and thus represents a milestone in small molecules targeting PPIs." (PMID 34017820, 2021). "In 2016, the FDA approved the BCL-2 selective inhibitor venetoclax for the treatment of chronic lymphocytic leukemia." (PMID 33883020, 2021). "The BCL2 inhibitor venetoclax has shown efficacy in several hematologic malignancies, with the greatest response rates in indolent blood cancers such as chronic lymphocytic leukaemia." (PMID 33318657, 2021). "Venetoclax is an oral, potent, selective inhibitor of BCL-2 that has proven effective in various hematological malignancies—especially chronic lymphocytic leukemia (CLL) or acute myeloid leukemia (AML)." (PMID 34680358, 2021). "In conclusion, the present study indicated that miRNA-15a acted in concert with fludarabine to exert synergistic anticancer efficacy against chronic lymphocytic leukemia, which attributed to the down-regulation of Mcl-1 and Bcl-2." (PMID 34319043, 2021). "A further example is venetoclax, a BCL-2 inhibitor that is approved for use in chronic lymphocytic leukemia (CLL) and acute myelogenous leukemia (AML)." (PMID 36046752, 2021).
chronic lymphocytic leukemia (continued). "High levels of Mcl-1 and Bcl-2 have been identified in B-cell chronic lymphocytic leukemia (CLL), a type of cancer that is extremely resistant to many types of treatment." (PMID 33805800, 2021). "Of note, BCL-2 inhibition via therapeutics like the BCL-2 inhibitor Venetoclax sensitizes cancer cells to apoptosis and has become indispensable for oncological treatment in Chronic Lymphocytic Leukemia (CLL) or Acute Myeloid Leukemia (AML)." (PMID 34063475, 2021). "Venetoclax, a selective inhibitor of BCL2, is a small molecule that can cross the blood-brain barrier and shows a potential efficacy in the treatment of chronic lymphocytic leukemia with central nervous system involvement." (PMID 34290987, 2021). "For example, the first report of altered miRNA deletion and downregulated expression of miR-15 and miR-16, two miRNAs thought to target the antiapoptotic factor B cell lymphoma 2 (BCL2) in chronic lymphocytic leukemia (CLL)." (PMID 33946400, 2021). "Given the remarkable clinical success of the Bcl-2 specific inhibitor, venetoclax or venclaxta, in treating relapsed or refractory chronic lymphocytic leukemia (CLL), many have sought to develop a Mcl-1 specific inhibitor." (PMID 34336857, 2021). "Venetoclax is a potent, BCL-2 selective BH3-mimetic that is clinically approved for use in chronic lymphocytic leukaemia." (PMID 32792521, 2020). "This first-in-class anti-BCL2 inhibitor is utilized in several other hematological malignancies, such as chronic lymphocytic leukemia (CLL) or acute myeloid leukemia (AML)." (PMID 33050025, 2020). "It was reported that miR-16 negatively regulated Bcl2 in chronic lymphocytic leukemia and prostate and hepatocellular carcinoma cancer cells." (PMID 32774515, 2020). "The most clinically advanced of these is venetoclax, which is a highly selective inhibitor of BCL2 that has transformed the treatment landscape for chronic lymphocytic leukemia (CLL)." (PMID 33198338, 2020). "Venetoclax, an inhibitor of the antiapoptotic protein BCL-2 used to treat chronic lymphocytic leukemia, is currently being evaluated in clinical trials as a monotherapy in high-risk myelodysplastic syndromes/acute myeloid leukemia." (PMID 32231817, 2020). "On the contrary, venetoclax is a highly selective and potent oral BCL-2 inhibitor approved in 2016 for the treatment of chronic lymphocyte leukemia (CLL) with 17p deletion." (PMID 32033196, 2020). "Venetoclax (ABT-199) is a selective BH3-mimetic Bcl-2 antagonist that is currently used in the clinic for treatment of chronic lymphocytic leukemia patients." (PMID 32708132, 2020). "In 2016, FDA approved the BCL-2 inhibitor Venetoclax for treatment of an aggressive form of chronic lymphocytic leukemia." (PMID 33353059, 2020). "Venetoclax, an FDA-approved Bcl-2 selective inhibitor for the treatment of chronic lymphocytic leukemia and acute myeloid leukemia (AML), is tolerated well in elderly patients with AML and has good overall response rates; however, resistance remains a concern." (PMID 32296028, 2020). "In chronic lymphocytic leukemia cells, expression of miR-16 is low due to a deletion in chromosome 13q14, and low levels of miR-16 inhibit apoptosis through targeting Bcl-2." (PMID 32411326, 2020). "Venetoclax (ABT-199, GDC-0199) is a highly selective BCL-2 inhibitor that represents the first approved agent of this class and is currently widely used in the treatment of chronic lymphocytic leukemia (CLL) as well as acute myeloid leukemia (AML)." (PMID 33139702, 2020). "Venetoclax (ABT-199/GDC0199) was the first-in-class BCL2 inhibitor approved for the therapy of chronic lymphocytic leukemia, and, recently, of acute myeloid leukemia (see Section 9)." (PMID 32197371, 2020). "For example, BCL2 selective inhibitor ABT-199 has shown high efficacy in the treatment of chronic lymphocytic leukemia (CLL), but it cannot induce apoptosis in certain tumor cell lines with MCL1 amplification." (PMID 33126914, 2020).
chronic lymphocytic leukemia (continued). "The drug resistance to BCL-2 has been reported in previous studies of chronic lymphocytic leukemia cells." (PMID 32796747, 2020). "In humans, miR-16 expression is inversely correlated to Bcl-2 expression in chronic lymphocytic leukemia and negatively regulate Bcl-2 at a posttranscriptional level." (PMID 32087719, 2020). "For example, anti-apoptotic BCL2 in chronic lymphocytic leukemia (CLL) and other cancers and BMI1 in gastric cancer as well as pancreatic cancer act as a stem cell marker and promoter of migration and invasion." (PMID 31061821, 2019). "On the other hand, venetoclax is already used as Bcl-2-specific inhibitor for chronic lymphocytic leukemia treatment." (PMID 31861874, 2019). "ABT‐199 (Venetoclax), a recently developed BH3 mimetic that selectively inhibits Bcl‐2, was introduced into the clinic for treatment of relapsed chronic lymphocytic leukaemia." (PMID 30266036, 2019). "Venetoclax, a BH3-mimetic FDA-approved drug for 17p-deleted refractory chronic lymphocytic leukemia, antagonizes BCL-2 and induces apoptosis." (PMID 31781977, 2019). "miR-15a/-16-1 are lost by 13q deletions in chronic lymphocytic leukemia, which leads to activation of miR-15/-16 target, BCL2." (PMID 30474694, 2019). "BH3 mimetics, in particular ABT-737 and ABT-199, induce a novel paradigm of cell death, characterised by excessive swelling of mitochondrial matrix and discontinuities in the OMM in BCL-2-dependent chronic lymphocytic leukaemia cells." (PMID 31341643, 2019). "The samples of patients with chronic lymphocytic leukemia of this trial were obtained, and the gene-expression studies demonstrated that expression of anti-apoptotic protein BCL2 and several BH3-only pro-apoptotic genes were upregulated on duvelisib therapy." (PMID 30782187, 2019). "Targeting BCL-2 is now considered a standard of care in the treatment of patients with chronic lymphocytic leukaemia and is emerging as a promising target in a number of haematological malignancies." (PMID 31717784, 2019). "The most successful of these drugs is the BCL-2 inhibitor venetoclax, which is approved for the treatment of chronic lymphocytic leukemia (CLL) and has shown considerable activity in therapy for other cancers, such as acute myeloid leukemia (AML)." (PMID 30008477, 2019). "In vitro, the combination of duvelisib and BCL2 inhibitor venetoclax resulted in enhanced apoptosis in chronic lymphocytic leukemia cells." (PMID 30782187, 2019). "Venetoclax is a highly selective BCL2 inhibitor and is considered a breakthrough therapy for refractory or relapsed chronic lymphocytic leukemia." (PMID 31336593, 2019). "The BCL-2-selective inhibitor venetoclax has been approved for use in chronic lymphocytic leukemia and is now being studied in a number of other hematologic malignancies." (PMID 30406027, 2018). "ABT-263 (Navitoclax) the orally active analogue of ABT-737 is a BCL-2 targeting agent currently in Phase II studies in small cell lung cancer and chronic lymphocytic leukaemia." (PMID 30305055, 2018). "To this end, we analyzed whole-exome sequencing data of eight chronic lymphocytic leukemia (CLL) patients that developed resistance upon BCL2-inhibition by venetoclax." (PMID 29463802, 2018). "The Bcl-2 inhibitor Venetoclax (ABT-199) was recently approved for the treatment of chronic lymphocytic leukemia and is currently tested in several ongoing clinical trials to treat multiple hematological malignancies." (PMID 29927992, 2018). "Recently the selective BCL2 inhibitor ABT199 was approved for the treatment of chronic lymphocytic leukemia with 17p deletion." (PMID 29352235, 2018). "Further, BCL2 in module 2 was a therapeutic target for chronic lymphocytic leukemia since it can regulate lymphocyte in blood by hindering cell apoptosis and PGD in module 5 was related with human cervical carcinoma." (PMID 30158870, 2018).
chronic lymphocytic leukemia (continued). "For example, in chronic lymphocytic leukaemia, the nucleolin activation in cells result in stabilization of Bcl-2 mRNA, with subsequent overproduction of Bcl-2 protein and avoidance of apoptosis." (PMID 30231586, 2018). "Another study deployed image-based profiling in primary chronic lymphatic leukemia (CLL) cells to identify small molecules effective in overcoming resistance against the BCL2 inhibitor Venetoclax." (PMID 30159406, 2018). "Successful clinical trials of venetoclax/ABT-199, a specific inhibitor of BCL-2, have led to its approval for a refractory form of chronic lymphocytic leukaemia and to scores of on-going trials for other malignancies." (PMID 29099483, 2018). "The BH3-mimetic venetoclax, selectively inhibiting BCL-2, often overexpressed in leukemia and lymphoma, has been approved for the treatment of refractory chronic lymphatic leukemia (CLL)." (PMID 29794999, 2018). "To date, venetoclax is the only small-molecule-selective BCL2 inhibitor that is approved by regulatory agencies, which narrowly focused on the treatment of chronic lymphocytic leukemia." (PMID 30404918, 2018). "In contrast, venetoclax, approved for treatment of chronic lymphocytic leukemia, avoids thrombocytopenia by higher BCL2 specificity." (PMID 29674644, 2018). "In Chronic lymphocytic leukemia patients Bcl2 expression is inversely correlated with miR-15a and miR-16-1 and both microRNAs negatively regulate Bcl2 at the posttranscriptional level." (PMID 27821806, 2017). "ABT199, which targets the BCL2/Bcl-xL interaction, is currently in phase 1 trials for chronic lymphocytic leukemia (CLL)." (PMID 29050234, 2017). "Recent studies have reported reversal of chemoresistance using an antisense approach to target Bcl-2 in models of chronic lymphocytic leukemia, non-Hodgkins lymphoma, and multiple myeloma." (PMID 28588271, 2017). "Meanwhile, lenalidomide was found to have inhibiting function of tumor growth through PI3K/Akt pathway, cereblon/p21, cyclin D1/p27 and Bcl-2 in chronic lymphocytic leukemia (CLL) and mantle cell lymphoma (MCL) in pre-clinical experiments." (PMID 27009084, 2016). "Venetoclax (ABT-199) is a specific oral B-cell lymphoma 2 (Bcl-2) inhibitor currently in clinical trials for the treatment of chronic lymphatic leukemia (CLL), acute myelogenous leukemia, small lymphocytic lymphomas, and multiple myeloma." (PMID 26927160, 2016). "For example, malignant chronic lymphocytic leukemia (CLL) cells express high levels of anti-apoptotic Bcl-2 and low levels of pro-apoptotic proteins such as Bax." (PMID 26230693, 2015). "Concomitantly, expression of BCL2 protein in B-lymphocytes from chronic lymphocytic leukemia patients carrying the -938 AA genotype was significantly increased compared with CC genotypes." (PMID 26656462, 2015). "In preclinical models, ABT-263 has demonstrated potent antitumor activity and clinical efficacy in Bcl-2-driven tumors, such as chronic lymphocytic leukemia." (PMID 24901320, 2014). "For example, miR-15a and miR-16-1 are reduced in about two thirds of B-cell CLL cases resulting in BCL-2 over-expression and the establishment of disease." (PMID 25621172, 2014). "In chronic lymphocytic leukemia, impaired degradation of BCL-2 mRNA is linked to nucleolin and/or microRNA expression, resulting in continuous production of BCL-2 protein and the subsequent survival of leukemic cells." (PMID 24832107, 2014). "As an example, hypo-methylation of the BCL-2 promoter has been reported in chronic lymphocytic leukemia (CLL)." (PMID 25621172, 2014). "miR-15a, along with miR-16, is commonly deleted in human chronic lymphocytic leukemia and known to target multiple oncogenes, including BCL2, MCL1, CCND1, and WNT3A." (PMID 23557329, 2013).